TLR4 (toll like receptor 4)
Diseases named in the same sentence as TLR4 in open-access papers (continued):
Sharing a sentence is not in itself a finding about the gene and the disease.
Insulin resistance (continued). "The specific knockout of TLR4 in myeloid cells inhibited insulin resistance in high-fat-diet-fed mice." (PMID 31744490, 2019). "By using in vivo and in vitro models, William L. Holland demonstrated that saturated fatty acids lead to ceramide biosynthesis by activating TLR-4 and that increased Cer is required for TLR-4 dependent insulin resistance." (PMID 31771303, 2019). "Accordingly, recent evidence reported that the knockdown of TLR4 in the arcuate nucleus protects rats from diet-induced weight gain, glucose intolerance and peripheral insulin resistance." (PMID 30906281, 2019). "It acts as an endogenous ligand for TLR4 that bridges FFAs and TLR4 promoting inflammation and insulin resistance." (PMID 30906281, 2019). "TAK-875 reduced the body weight and inflammatory factors, inhibited the insulin resistance, rebalanced the number and distribution of α or β-cells, and inhibited the islet cell apoptosis and of the expression of TLR4-NF-κB subunit P65 of obese rats." (PMID 31934590, 2019). "Fetuin A stimulates the production of pro-inflammatory cytokines from adipocytes and macrophages and acts as an endogenous ligand for Toll-like receptor 4, which enables free fatty acids to activate Toll-like receptor 4 signaling to induce insulin resistance." (PMID 30670052, 2019). "Human cross-sectional studies showed that TLR4 expression is increased in adipose tissue and monocytes of obese or diabetic patients, which is correlated with the severity of insulin resistance." (PMID 31582899, 2019). "Additional studies have suggested that free fatty acids (FFAs) can induce TLR4-dependent insulin resistance, which requires fetuin-A as an endogenous ligand to mediate the interaction between FFAs and TLR4." (PMID 31507457, 2019). "Studies have implicated an important role for TLR4 in metabolic inflammation; long chain SaFAs can activate TLR4 signal transduction and promote inflammatory cytokine expression and insulin resistance." (PMID 31040846, 2019). "In fact, TLR4 is suggested to be a molecular link among nutrition, lipids, inflammation, insulin resistance, and AD." (PMID 31849586, 2019). "Our recent findings evidenced that central Resistin/TLR4 signaling pathway promotes the onset of hypothalamic inflammation and insulin resistance." (PMID 30906281, 2019). "Recently, several studies have demonstrated that TLR4 signaling is important for HFD-induced insulin resistance by mediating inflammatory responses within adipose tissue and skeletal muscle." (PMID 30054551, 2018). "In the insulin resistance models, Rhizoma coptidis acts on the TLR4/JNK/NF-κB inflammatory pathways and inhibits the activities of MCP-1, IL-6, TNF-α, JNK and NF-κB." (PMID 29930696, 2018). "Pharmacological inhibition of TLR4 also protects mice against HFD-associated adipose inflammation and fibrosis and insulin resistance." (PMID 30396359, 2018). "There is a large body of data derived mainly from in vitro and animal studies linking TLR4 to insulin resistance." (PMID 29649324, 2018). "In light of this and studies suggesting a direct involvement of TLR4-mediated inflammation in the development of HF diet-induced hepatic steatosis and insulin resistance, there is a concerted effort directed at developing therapeutics targeting TLR4 signaling." (PMID 29666152, 2018). "Conversely, the presence of insulin resistance favors the expression of TLR4, suggesting that insulin resistance promotes inflammation." (PMID 29601492, 2018). "The excess of FFAs influences the development of insulin resistance through the activation of Toll-Like Receptors 4 (TLR-4) on the plasma membrane, subsequently activating the inflammatory proteins c-Jun N-terminal kinase (JNK), IκB kinase and NF-κB." (PMID 30705633, 2018). "Reduced TLR4 expression and function protected against insulin resistance in a mouse model of systemic lipid infusion, demonstrating a role for TLRs in lipotoxic disorders." (PMID 30666212, 2018).
Insulin resistance (continued). "Endotoxemia and TLR4 signaling control the production of proinflammatory cytokines in target tissues, which lead to chronic inflammation and insulin resistance in HFD-fed rats." (PMID 30112382, 2018). "Rhizoma coptidis plays a therapeutic role in insulin resistance partly by regulating the TLR4/JNK/NF-κB pathways and Akt/AMPK/GLP-1/ERS pathways." (PMID 29930696, 2018). "LPS is an endotoxin related to insulin resistance, once it binds TLR4 and triggers intracellular inflammatory responses." (PMID 29412381, 2017). "We also used siRNA to determine the mechanisms and the crosstalk between IL-6 and TLR4 expression via STAT3 in the development of insulin resistance and glucose intolerance in the skeletal muscle." (PMID 28706484, 2017). "Nox isoforms such as Nox2, Nox3, and Nox4 have a critical role in hepatocyte, endothelial cell, skeletal muscle cell, and adipocyte insulin resistance, and Nox-derived ROS contribute to TLR4 activation and signaling." (PMID 29081894, 2017). "Fetuin-A is known as an endogenous ligand that binds to free fatty acids and functions as an endogenous ligand for the Toll-like receptor TLR-4 thereby linking metabolic diseases (hyperlipidemia, insulin resistance) and subclinical inflammation." (PMID 28781590, 2017). "Apart from LPS, fatty acids can also increase TLR4 signaling in several cell types including adipocytes and macrophages and promote visceral obesity and insulin resistance." (PMID 29163467, 2017). "Several studies reported that insulin resistance and hepatic steatosis were suppressed in TLR4 and CD14 mutant mice." (PMID 28349245, 2017). "This upregulation is pivotal in the development of insulin resistance via its effect on mCD14 and toll-like receptor (TLR)-4." (PMID 27375553, 2016). "FetA knockdown in mice with hyperglycemia resulted in inactivation of the TLR4-MyD88-dependent signaling pathway, whereas selective administration of FetA induced inflammatory signaling and insulin resistance." (PMID 26959040, 2016). "TLR4-Myd88 signaling is involved in the development of insulin resistance in high fat diet fed mice, reinforcing the notion that lipid-receptors enable innate immunity to sense the lipid and glucose environment and to modulate the inflammatory responses." (PMID 27545843, 2016). "The crucial role of TLR4 in NAFLD pathogenesis has been demonstrated in TLR4-deficient mice, that display lower levels of inflammatory mediators and fail to develop NAFLD or insulin resistance." (PMID 27657051, 2016). "On the other hand, loss-of-function mutation in TLR4 prevents HFD-induced obesity and insulin resistance." (PMID 25814786, 2015). "Endotoxemia and TLR4 signalling control the production of pro-inflammatory cytokines in target tissues and lead to chronic inflammation and insulin resistance in HFD-fed mice." (PMID 26102296, 2015). "The present study is the first to evaluate the effect of pharmacological TLR4 inhibition on acute and chronic fat-induced insulin resistance in vivo." (PMID 26196892, 2015). "Pharmacological TLR4 inhibition provides partial protection against acute and chronic fat-induced insulin resistance in vivo." (PMID 26196892, 2015). "This is in contrast with studies in other insulin-sensitive tissues that reported a link between TLR4 activation and insulin resistance through the upregulation of pro-inflammatory cytokines." (PMID 26539824, 2015). "The results from the present study indicate that TLR4 expression by liver resident cells plays a key role in translating the effects of chronic periodontitis into the development of insulin resistance and glucose intolerance." (PMID 26317345, 2015). "While most previous studies support the paradigm that genetic disruption of TLR4 protects against whole-body insulin resistance, the effect of TLR4 disruption on body weight and adiposity in response to a HFD is less clear." (PMID 26196892, 2015).
Insulin resistance (continued). "Recently, TLR4 has emerged as a strong candidate for a cellular link between inflammation and insulin resistance." (PMID 26539824, 2015). "Whereas the role of TLR4 signaling in insulin resistance is a well-established concept the specific roles of TLR4 expressing cells in respect to the pathogenesis of T2D are still an unexplored area." (PMID 24594974, 2014). "Conversely, overexpression of TLR4 by adenovirus in the livers of wild-type mice induced insulin resistance even under a ND." (PMID 24614850, 2014). "Toll-like receptor 4 (TLR4) has received much attention in the recent years due to its role in the development of insulin resistance in T2D." (PMID 24594974, 2014). "Forced expression of human PRSS8 or TLR4 depletion in db/db mouse livers ameliorated the insulin resistance." (PMID 24614850, 2014). "Restoration of PRSS8 expression in livers of HFD, LKO and db/db mice decreases the TLR4 level and ameliorates insulin resistance." (PMID 24614850, 2014). "Over the last few years, there has been growing evidence for fatty acid-induced lipotoxicity, such as insulin resistance, through toll-like receptor 4 (TLR4)." (PMID 24357461, 2014). "Fetuin-A has recently been shown to be an endogenous ligand for Toll-like receptor 4 (TLR4) through which it has a critical role in stimulating adipose tissue inflammation resulting in insulin resistance." (PMID 24800810, 2014). "In this study, we demonstrate that the serine protease prostasin (PRSS8) protects the liver from chronic inflammation via the proteolytic cleavage and shedding of TLR4, consequently preventing the liver from developing insulin resistance." (PMID 24614850, 2014). "This process stimulates adipocyte TLR4 levels, which results in the release of chemokines, which in turn recruits inflammatory macrophages into the adipose tissue, leading to insulin resistance." (PMID 24281248, 2014). "Studies in animal models showed that both receptors, TLR-2 and TLR-4, are related to atherosclerosis, insulin resistance and diabetes, features present in the MetS." (PMID 25329057, 2014). "We have shown that 12/15-LO oxidation products activate TLR4 in macrophages, suggesting a possible connection between 12/15-LO and TLR4 activation in the pathogenesis of insulin resistance." (PMID 25251155, 2014). "We employed gene silencing as an independent, albeit complementary method to examine the role of TLR4 on LPS-induced insulin resistance." (PMID 23704966, 2013). "ER stress and TLR4 signaling are both major players in the development of insulin resistance induced by lipid excess." (PMID 23741455, 2013). "Ablation of TLR4 in transgenic mice confers partial protection against insulin resistance induced by lipid infusion or high-fat diet (HFD)." (PMID 23741455, 2013). "Hematopoietic cell-specific deletion of TLR4 in mice attenuated HFD-induced insulin resistance in adipose and the liver." (PMID 23964268, 2013). "TLR4 has been shown to play a role in vascular insulin resistance due to its ability to bind free fatty acids and activate inflammatory pathways." (PMID 23840960, 2013). "There is therefore a conflict regarding the activity of the TLR4/MyD88 axis in diet-induced obesity and insulin resistance, which remains to be elucidated in future studies." (PMID 23964268, 2013). "There is a body of evidence suggesting that TLR4 is an attractive candidate for linking innate immune responses to insulin resistance." (PMID 24064574, 2013). "In fact, inflammatory cytokines (for example, TNF-alpha) and Toll-like receptor 4 (TLR4), an obligatory receptor for bacterial LPS, are important participants in insulin resistance in critical illness." (PMID 23375099, 2013). "Proteins including fetuin-A and resistin are reported to be endogenous ligands for TLR4 and induce insulin resistance." (PMID 24064574, 2013). "Adipocytes produced IL-6 via TLR4 activation and the upregulation of osteopontin further exacerbated adipose tissue inflammation and insulin resistance." (PMID 23191980, 2012).
Insulin resistance (continued). "Activation of TLR2 and TLR4 with fatty acids contributes to NF-κB activation, increased inflammation, and insulin resistance." (PMID 22384159, 2012). "Upon binding to the complex of CD14 and toll-like receptor 4 on the surface of innate immune cells, LPS can induce systemic inflammation, which eventually impairs insulin sensitivity and induces insulin resistance-related metabolic disorders." (PMID 22880019, 2012). "Ceramide generation has recently been shown to mediate saturated fatty acid-induced insulin resistance in skeletal muscle via TLR4 signalling." (PMID 22558381, 2012). "TLR4 mRNA and protein expression and TLR4 signaling were increased in recently-diagnosed T2D and TLR4 levels were positively correlated with the glucose level and severity of insulin resistance in this population." (PMID 23304117, 2012). "These mice fail to mount a pro-inflammatory response to LPS, and thus are protected from CD14/TLR4-dependent insulin resistance." (PMID 22253759, 2012). "The role of TLR2 and TLR4 has been suggested in conventional insulin resistance (IR) target tissues like skeletal muscle and adipose tissue of Type 2 diabetes subjects." (PMID 23191980, 2012). "Greater understanding of the role of TLR-4 in relation to dietary fat is important in understanding the pathobiology of insulin resistance and DM2." (PMID 21388548, 2011). "TLR4 mutant mice compared to WT mice had significantly higher fasting blood glucose, serum insulin, insulin resistance, serum leptin, and serum cholesterol when they received TF diet (P < 0.05)." (PMID 21314942, 2011). "In vivo studies have reported that FO is incorporated into the plasma membrane where it inhibits downstream signaling of TLR-4 leading to decreased insulin resistance." (PMID 21388548, 2011). "Insulin resistance we observed in TLR4 mutant mice in response to TF diet is likely secondary to the increased adiposity of the TLR4 mutant mice." (PMID 21314942, 2011). "It has been well established that activation of TLR4 by microbial endotoxin, LPS (TLR4 agonist), triggers the host's innate immune and inflammatory responses leading to the upregulation of pathways relating to insulin resistance and dyslipidemia." (PMID 21314942, 2011). "In vivo studies are limited linking dietary fatty acids with TLR-4 signaling and inflammation, insulin resistance, and adiposity." (PMID 21388548, 2011). "It is likely that TLR-4 is a possible link between dietary fatty acids and inflammation, insulin resistance, and DM2." (PMID 21388548, 2011). "Several mouse model studies have demonstrated the importance of TLR4 and its signaling components in diet-induced insulin resistance, inflammation, and atherosclerosis." (PMID 20814545, 2010). "In the next sections, we will highlight tissue-specific effects of TLR4 activation and its role in insulin resistance." (PMID 20814545, 2010). "Perhaps most interesting among these is Tlr4, which can be activated by nutritional fatty acids to promote insulin resistance." (PMID 21152033, 2010). "In these individuals, TLR4 protein expression in muscle correlates with the severity of insulin resistance." (PMID 20814545, 2010). "Recent data from ours and other groups have shown that inflammatory signaling through TLR4 plays an important role in diet-induced insulin resistance and diabetes." (PMID 19340313, 2009). "TLR4 has, indeed, emerged as a critical molecular link between inflammation and insulin resistance." (PMID 41226745, 2025). "Increased FFA promotes TLR4 expression and activation, triggering insulin resistance." (PMID 40076851, 2025). "In addition, bacterial-derived endotoxins enter the liver through the portal vein, activating the TLR4/NF-κB pathway and inducing intrahepatic inflammatory response and insulin resistance." (PMID 41048505, 2025).
Insulin resistance (continued). "After bacterial lysis, LPS enters the circulation and triggers systemic chronic low-grade inflammation through activation of Toll-like receptor 4 (TLR4), which in turn induces serine phosphorylation of insulin receptor substrate-1, ultimately leading to the development of insulin resistance." (PMID 41488463, 2025). "Microbial LPS also stimulates TLR4, worsening insulin resistance." (PMID 41374093, 2025). "TLR-4 activation also increases iNOS expression, leading to an increase in serum NO levels, which contribute to an oxidative stress response that potentiates hyperglycemia and insulin resistance." (PMID 40260376, 2025). "TLR4 signaling also induces insulin resistance by disrupting insulin receptor substrate pathways." (PMID 41190061, 2025). "In addition, fetuinA enhances insulin resistance by decreasing the expression of glucose transporter-4 (GLUT-4) proteins by activating toll-like receptor 4 (TLR-4) in skeletal muscles." (PMID 41341131, 2025). "The role of lipopolysaccharides (LPSs) and Toll-like receptor 4 (TLR-4) signaling in promoting pro-inflammatory cytokine release and contributing to insulin resistance and metabolic dysfunction may also be relevant in the context of SIBO." (PMID 40284229, 2025). "Targeting key nodes within this network—such as the IL-17 receptor, TLR4, or HIF-1α—may offer a multidimensional therapeutic strategy for insulin resistance (IR) and its associated complications." (PMID 40625623, 2025). "Moreover, FFA induces insulin resistance through multiple pathways, including Toll-like receptor 4 signaling activation, diacylglycerol accumulation, and ceramide synthesis." (PMID 39966964, 2025). "Fetuin-A stimulates the synthesis of proinflammatory cytokines in the adipocytes and macrophages and might act as a ligand for Toll-like receptor 4, including insulin resistance by enabling free fatty acids to activate Toll-like receptor 4 signaling." (PMID 39513077, 2024). "Furthermore, TLR4 knockout was observed to reduce high-fat diet-induced insulin resistance in mice, and inhibiting central IKKβ/NF-κB decreased insulin resistance in the brain." (PMID 38818523, 2024). "Moreover, TLR4 inhibition prevents insulin signaling dysfunction and improves behavioral and molecular impairments, highlighting the critical role of TLR4 in the development of insulin resistance in PD pathology." (PMID 39830652, 2024). "Cbl-b over-expression inhibited saturated fatty acid-induced toll-like receptor 4 (TLR4) signaling, as it mediates TLR4 ubiquitination and degradation in macrophages, leading to modulated TLR4 protein levels on the cell surface, thereby improving insulin resistance in the liver." (PMID 39188976, 2024). "Thus, TLR4 emerges not only as a critical receptor in the inflammatory pathway but also plays a pivotal role in the development of insulin resistance." (PMID 38379904, 2024). "The activation of Toll-like receptor 4 (TLR4) by FFA is another trigger of insulin resistance." (PMID 38892574, 2024). "Resistin exacerbates insulin resistance and inflammatory metabolic diseases in adipocytes, hepatocytes, myocytes, endothelial cells, and other cells by influencing the pattern recognition receptor TLR4." (PMID 39220365, 2024). "A growing body of evidence is now linking fetuin-A to adipose tissue insulin resistance by inducing TLR4 signalling, which might seem especially important in South Asians." (PMID 38786765, 2024). "Previous data have shown that LPS binding to TLR4 is associated with insulin resistance, because mice lacking TLR4 are protected from suppressed insulin signaling and insulin-mediated changes in glucose metabolism." (PMID 38257161, 2024). "White adipose tissue stresses or lipopolysaccharides increase NF-κB and c-Jun N-terminal kinase signaling, upregulate the production of inflammatory cytokines such as TNF-α and IL-6, and promote insulin resistance in adipocytes and macrophages via TLR4/TLR2 activation." (PMID 38292473, 2024).